PDK1 (pyruvate dehydrogenase kinase 1)
Diseases named in the same sentence as PDK1 in open-access papers (continued):
Sharing a sentence is not in itself a finding about the gene and the disease.
Cognitive impairment (6 papers, 2017 to 2026). Abnormal cognition is characterized by deficits in thinking, reasoning, or remembering. "These cognitive deficits are interesting to note since the mutations related to the PDK1 and Akt signaling pathway, such as those in Akt2 knockout mice, presented a higher anxiety-like and depressive-like behavior, but were cognitively intact." (PMID 32457586, 2020). "Mutation of PDK1 in mice leads to cognitive impairments and exacerbated disruptive behaviours." (PMID 33276438, 2020). "Since it has been demonstrated that neuron loss and synaptic loss directly contribute to cognitive impairments in neurodegenerative disease, we reason that learning deficit in PDK1 cKO mice is likely caused by massive loss of neurons and synapses in the cortex." (PMID 29104535, 2017). "Enhancing PDK1 expression in the hippocampus ameliorated STZ-induced cognitive impairment and neuronal degeneration in mice." (PMID 37935660, 2023). "In order to explore the mechanism by which SQW improves STZ-induced cognitive impairment, we detected PI3K, PDK1, p-AKT, AKT, and GSK3β expression." (PMID 35741643, 2022).
endometriosis (6 papers, 2021 to 2025). The growth of functional endometrial tissue in anatomic sites outside the uterine body. "In clinical studies, PDK1 inhibitor DCA has been confirmed to contribute to the reduction of pain in endometriosis patients." (PMID 40573210, 2025). "In previous preclinical and early clinical studies, DCA was shown to restore mitochondrial function by inhibiting PDK1, reduce lactic acid production, and alleviate endometriosis-related pain." (PMID 40573210, 2025). "Glucose transporter 1 (GLUT1), lactate dehydrogenase A (LDHA), and pyruvate dehydrogenase kinase 1 (PDK1) have been suggested as key enzymes for maintaining glycolytic metabolism in endometriosis." (PMID 35444541, 2022). "Increased expression of hypoxia-inducible factor 1α (HIF1α), pyruvate dehydrogenase kinase 1 (PDK1) and lactate dehydrogenase (LDHA) in adult patients with endometriosis suggests metabolic reprogramming patterns similar to those of cancers." (PMID 38673823, 2024). "Other targets for endometriosis management could be PDH and PDK1 that play key roles for oxidative and glycolytic metabolism." (PMID 39169201, 2024). "In addition, several studies have shown that targeting LDHA or PDK1 might be an effective non-hormonal strategy for the treatment of endometriosis by reducing cell survival and inducing apoptotic cell death." (PMID 35444541, 2022).
head and neck cancer (6 papers, 2014 to 2022). A primary or metastatic malignant neoplasm affecting the head and neck. "We further found that PDK1 expression was also markedly elevated in head and neck cancer, and the expression of PDK1 was significantly and positively correlated with the expression of FOXM1 in patients with head and neck cancer from the TCGA database." (PMID 35656815, 2022).
heart failure (6 papers, 2013 to 2022). Inability of the heart to pump blood at an adequate rate to meet tissue metabolic requirements. "Previous studies have reported that Tamoxifen-inducible and heart-specific disruption of PDK1 in adult mice causes severe and lethal heart failure." (PMID 25781322, 2015). "It is unclear if the changes are related to the reduction in PDK1 or due to some other changes associated with heart failure and outward potassium channels." (PMID 25781322, 2015). "Mice with PDK1 deletion have markedly reduced myocardium, smaller cardiomyocytes, thinner ventricles and enlarged atria, which eventually leads to heart failure and sudden death within 11 weeks; however, the underlying mechanisms of abnormal electrophysiological basis related deaths are not clear." (PMID 25781322, 2015). "Pdk1 hypomorphic mice have smaller cardiovascular organ volumes, and Pdk1 conditional abstraction in muscle cells leads to heart failure and minimizes lifespan." (PMID 36362447, 2022). "In animal experiments, PDK1 knockout mice die suddenly of heart failure; however, the potential electrophysiological basis lead to the sudden death has not been determined." (PMID 25781322, 2015). "PDK-1 regulates contractility in cardiac muscle and prevents heart failure, which is consistent with its ability to sustain rapid pharyngeal pumping during starvation." (PMID 23700438, 2013). "Furthermore, the PI3K/PTEN signaling pathway, which is upstream of PDK1 and Akt, is involved in a wide variety of diseases including myocardial hypertrophy and contractility, heart failure, and preconditioning." (PMID 25781322, 2015). "Lack of PDK1 in mouse cardiac muscle has been shown to be associated with less thickening of the ventricular wall and lead to heart failure." (PMID 25781322, 2015). "In previous studies, IL-18 was found to act via PI3K/PDK1/Akt/GATA4-induced cardiac hypertrophy and play an important role in cardiac remodeling and heart failure." (PMID 37551283, 2022). "PDK1 expression was unchanged in the heart failure group, suggesting that oxygen delivery is not a significant factor modifying PDH expression in end-stage failure." (PMID 30881593, 2019). "The protein expression levels of PDK1 and PDK2 were unaffected by heart failure." (PMID 30881593, 2019). "Moreover, PDK1 and its upstream or downstream factors, including phosphatidyl inositol 3-kinase (PI3K), Akt and mTOR, are involved in heart failure and pathologic heart remodeling." (PMID 25781322, 2015).
lung adenocarcinoma (6 papers, 2013 to 2024). A carcinoma that arises from the lung and is characterized by the presence of malignant glandular epithelial cells. "Histological analysis of samples from human adenocarcinomas carrying mutant K-Ras12 at different stages of cancer progression, have shown a correlation between loss of p38α, activation of Pdk1 (pPdk1) within the tumors and progression of human lung adenocarcinomas into malignant stages." (PMID 24265727, 2013). "Next, we investigated the importance of the RING-like domain of RNF126 on the destabilization of endogenous PDK1 in human lung adenocarcinoma PC8 cells." (PMID 27462466, 2016). "For example, simultaneous inhibition of multiple glycolytic enzymes (PDK1 and LDH-A) is a promising new treatment for lung adenocarcinoma." (PMID 39588377, 2024).
lymphoma (6 papers, 2016 to 2023). A malignant (clonal) proliferation of B- lymphocytes or T- lymphocytes which involves the lymph nodes, bone marrow and/or extranodal sites. "As expected, BCR- lymphoma cells show decreased levels of GSK-3β phosphorylated on Ser9 through PI3Kδ/phosphoinositide-dependent kinase 1 (PDK1)/Akt signaling." (PMID 35681507, 2022). "Exposure of lymphoma cells to H2O2 to DLA cells increased phosphorylation of PDK1." (PMID 27494022, 2016). "The expressions of HK2 and PDK1 in the presence of exosomes from CAF1 and CAF2 were higher than those from CAF3 and CAF4, indicating that glycolysis in lymphoma cells was increased in the presence of exosomes from CAF1 and CAF2." (PMID 33994542, 2021). "In lymphoma cells co-cultured with CAF1 and CAF2, the expressions of HK2 and PDK1, key enzymes of glycolysis, were higher than in those with CAF3 and CAF4." (PMID 33994542, 2021). "Both PI-103 & quercetin suppressed the enhanced level of ROS and significantly down-regulated phosphorylation of AKT, PDK1, BAD and level of TNFR1 as well as increased the level of PTEN in H2O2 induced lymphoma cells." (PMID 27494022, 2016).
myocardial infarction (6 papers, 2017 to 2025). Gross necrosis of the myocardium, as a result of interruption of the blood supply to the area, as in coronary thrombosis. "In previous studies in mice, inhibition of miR-375 by interleukin-10 administration or anti-miR-375 therapy enhanced cardiac recovery and reduced inflammatory response after myocardial infarction by activation of the PDK-1-AKT pathway." (PMID 34708100, 2021). "Here we show that carbacyclin induces cardiomyocyte proliferation via a PPARδ/PDK1/p308Akt/GSK3β/β-catenin-pathway and that activated PPARδ signaling after myocardial infarction (MI) induces cardiomyocyte cell cycle activity and improves scarring as well as cardiac function." (PMID 28621328, 2017).
squamous cell carcinoma (6 papers, 2011 to 2025). A carcinoma arising from squamous epithelial cells. "For example, squamous cell carcinomas and adenocarcinomas express high levels of PDK1 with evidence of PDC inactivation during metastasis." (PMID 36914879, 2023). "Similarly, an in vivo model of squamous cell carcinoma driven by constitutive activation of Src showed increased levels of activated PDK1, STAT3, and ERK1/2 in the lesioned tissue." (PMID 30622697, 2019).
viral infection (6 papers, 2019 to 2025). "Collectively, these data indicated that PDK1 is essential for Tfh cell differentiation during viral infection." (PMID 33595435, 2021). "To specifically delete PDK1 at the late stage of Tfh cell differentiation, we treated WT or Pdk1fl/fl::Rosa26CreER mice with tamoxifen from day 4 to day 7 post-viral infection." (PMID 33595435, 2021). "Concurrently, genes associated with hypoxic stress, including PDK1, BNIP3L, VEGF, and LOX, were significantly upregulated in both EBOV- and MARV-infected HCOs, consistent with prior reports of hypoxia-related signaling during viral infection." (PMID 41284734, 2025). "In this study, we explore the knowledge gap whether and how PDK1 plays essential roles in Tfh cell differentiation elicited by acute viral infection and protein immunization." (PMID 33595435, 2021). "PDK1 also shows a partial nuclear localization, so the upregulation of PDK1 expression during viral infection could disrupt nuclear histone acetylation, which could be restored by HDAC inhibitors such as R-BHB." (PMID 33014275, 2020). "Contrary to expectations, we found either enforced PDK1 or PDP1 expression resulted in enhanced CD8+ T cell metabolic capacity and increased primary and secondary responses in a virus infection model." (PMID 40857407, 2025). "Therefore, while PDK1- and PDP1-transduced CD8+ T cells mounted better responses in the virus infection model, their antitumor responses were compromised." (PMID 40857407, 2025). "To elucidate whether PDK1 regulates Tfh cell differentiation, we first evaluated the expression of PDK1 in bifurcation of effector CD4+ T cells into Tfh or Th1 cells upon acute viral infection." (PMID 33595435, 2021). "To test the role of enforced PDK1 or PDP1 expression on the T cell response in vivo, we elected to use the MHV-68 model system, a persistent virus infection model that induces a potent CD8+ T cell response does not subject T cells to exhaustion." (PMID 40857407, 2025).
atherosclerosis (5 papers, 2017 to 2025). A disease characterized by the build-up of fatty material and calcium deposition in the arterial wall resulting in partial or complete occlusion of the arterial lumen. "To understand the mechanisms underlying miR-210 and PDK1 interaction in atherosclerosis, we further identified the potential target sites of PDK1 to miR-210." (PMID 28536634, 2017). "Our results suggest that atherosclerosis-associated endothelial cell apoptosis might result from abundant miR-210 that inhibits P13K/Akt/mTOR signaling activation by directly targeting PDK1." (PMID 28536634, 2017). "For example, miRNA-210 induces the apoptosis of ECs by targeting PDK1 and thus aggravates atherosclerosis." (PMID 35222741, 2022). "We were interested in determining the involvement of PDK1 and P13K/Akt/mTOR signaling in the miR-210 regulatory apoptotic effect in atherosclerosis." (PMID 28536634, 2017). "Our study identified the pro-atherosclerotic role of miR-210 by promoting endothelial apoptosis partially through targeting PDK1 to suppress the P13K/Akt/mTOR signaling pathway, providing new insight into the treatment of atherosclerosis." (PMID 28536634, 2017). "Repression of PDK1 due to miR-210 upregulation was found to critically contribute to endothelial apoptosis in the setting of atherosclerosis." (PMID 28536634, 2017). "Our findings also showed that PDK1 is an essential miR-210 target in regulating endothelial apoptosis of atherosclerosis by inhibiting P13K/Akt/mTOR signaling activation." (PMID 28536634, 2017). "In this study, we found that miR-210 was upregulated by directly targeting 3-phosphoinositide-dependent protein kinase-1 (PDK1) in vascular endothelial cells in an atherosclerosis mouse model and in human aortic endothelial cells (HAECs) treated with oxidized low-density lipoprotein (ox-LDL)." (PMID 28536634, 2017). "In our study, we found that reversing PDK1 expression could significantly resist miR-210-induced cell apoptosis in ox-LDL-treated HAECs, implying an anti-apoptotic role of PDK1 in the development of atherosclerosis." (PMID 28536634, 2017). "Although several factors related to hypoxia such as HIF1A and downstream targets of the HIF pathway, such as PDK-1 and VEGF, have been studied in detail in atherosclerosis, HIF3A expression has not previously been reported." (PMID 40034249, 2025).
Burkitt lymphoma (5 papers, 2013 to 2022). A rare form of malignant mature B-cell non-Hodgkin lymphoma. "It is known that the hypoxia-inducible factor 1-alpha (HIF1A) and MYC proteins cooperatively regulate expression of the HK2 and PDK1 genes, respectively, in the Burkitt lymphoma (BL) cell line P493-6, carrying an inducible MYC gene repression system." (PMID 26312753, 2015). "Moreover, hypoxia promotes the expression of the enzyme pyruvate dehydrogenase kinase 1 (PDK1) in human Burkitt’s lymphoma cell line P493-6, in a time-dependent manner." (PMID 30015560, 2019). "In Burkitt lymphoma cells, elevated Myc and HIF-1α induce the expression of HK2 and PDK1, enzymes that inactivate pyruvate dehydrogenase and decrease mitochondrial respiration, thereby favoring aerobic glycolysis in malignant B cells." (PMID 36115986, 2022). "Relevant to the present results, selective induction of HK2 and pyruvate dehydrogenase kinase-1 (PDK1) by hypoxia (and HIF-1α and c-myc) was observed in a previous study of human P493-6 B-lymphoblastoid cells, a model for human Burkitt’s lymphoma." (PMID 23866118, 2013).
cardiac hypertrophy (5 papers, 2015 to 2025). "In cardiac hypertrophy, Sirt1 may act in the cytosol, where it deacetylases Akt and PDK1, PDK1 phosphorylates Akt, which becomes active and promotes hypertrophy." (PMID 30304806, 2018). "Under pressure overload, VCP expression was decreased in the hearts of WT mice and the inhibitory binding of VCP with AKT at T308 was removed, which allows AKT to become phosphorylated by PI3K/PDK1 on threonine 308, then subsequently activating mTORC1 signaling and inducing cardiac hypertrophy." (PMID 28799247, 2017). "It has been known that pAKT T308 was upregulated by TAC via the activated PI3/PDK1 signaling, resulting in the activation of mTORC1 substrates, which leads to cardiac hypertrophy; however, the change and the role of pAKT S473 in the TAC‐induced hypertrophy remain controversial." (PMID 28799247, 2017). "In addition, in some pathophysiological conditions, including cardiac hypertrophy and tumor progression, Sirt1 clearly activates protective signaling pathways controlled by AKT and PDK1." (PMID 30304806, 2018).
cholesteatoma (5 papers, 2020 to 2025). A pathologic process characterized by the proliferation of keratinizing squamous epithelium resulting in the accumulation of keratin and cells in the middle ear and/or mastoid. "For example, one study indicated that the PDK1/PTEN/AKT/GSK3β/CyclinD1 pathway was involved in the proliferation of keratinocytes in cholesteatoma." (PMID 41369408, 2025). "Another study also revealed that PPARδ/PDK1/PTEN/AKT/GSK3β/Cyclin D1 pathway was involved in the proliferation of keratinocytes in cholesteatoma." (PMID 35151320, 2022). "The cholesteatoma keratinocytes were inoculated with varied CoCl2 concentrations and the contents of PDK1、Akt and p‐Akt were assessed with western blotting." (PMID 34522167, 2021). "The proliferation and cellular HIF-1α, p-PDK1 and p‐Akt expression levels of cholesteatoma keratinocytes were assessed in vitro." (PMID 34522167, 2021). "Taken together, our findings indicate that PPAR β/δ activation promotes cell proliferation in cholesteatoma keratinocytes through the regulation of the PDK1/AKT/PTEN/GSK3β/Cyclin D1 pathway." (PMID 33424958, 2020). "Overall, our data suggested that the proliferating effect of PPAR β/δ on the cholesteatoma keratinocytes was mediated by the positive regulation of the PDK1/PTEN/AKT/GSK3β/Cyclin D1 pathway." (PMID 33424958, 2020). "In summary, we demonstrated that ligand activation of PPAR β/δ regulates cell proliferation in cholesteatoma keratinocytes and that upregulation of PDK1 and modulation of the AKT/PTEN/GSK3β/Cyclin D1 pathway may be involved." (PMID 33424958, 2020).
invasive breast carcinoma (5 papers, 2005 to 2022). A carcinoma that infiltrates the breast parenchyma. "Tissue microarray analysis of human invasive breast cancer has revealed that phosphorylation of PDK1 on Ser-241 was strongly enhanced in 90 % of the samples tested." (PMID 26684827, 2015). "We therefore examined phosphorylation of PDK-1 at residue S241 in a total of six normal breast tissues and 89 invasive breast carcinomas using IHC staining on TMA slides." (PMID 16288304, 2005). "Consistent findings were obtained as greater than 70% of invasive breast carcinomas expressed moderate to high levels of phosphorylated PDK-1, AKT, p70S6K, and EGFR." (PMID 16288304, 2005). "For example, immunohistochemistry staining analysis of 89 invasive breast cancer tissues and six normal mammary tissues found that more than 70% of invasive breast cancer tissues expressed high levels of phosphorylated PDK-1, AKT, p70S6K, and EGFR, relative to normal mammary tissues." (PMID 34571875, 2021). "MT1-MMP expression has been linked to invasive breast cancer and lymph node and distant metastases, which is consistent with the increased gene expression of two MT1-MMP ECM-related substrates, type I collagen, and decorin in Comma/PDK1 cells." (PMID 16551362, 2006). "Interestingly, increased PDK-1 phosphorylayion was significantly correlated with invasive breast carcinoma (P< 0.05) as illustrated by the Student's t-test using SPSS software." (PMID 16288304, 2005). "Elevated phosphorylation levels for the proteins PDK-1, AKT, p70S6K, EGFR, and Stat3 were highly correlated with invasive breast cancers (p < 0.05)." (PMID 34571875, 2021).
metastatic tumors (5 papers, 2015 to 2025). "The tumor suppressive miR-451a, a suppressor of PDK1, is downregulated in metastatic vs non-metastatic tumors." (PMID 35666359, 2022). "Further, few studies have shown that PDK1 expression is significantly higher in the metastatic tumour than BPH, PIN lesions, and localised prostate tumours." (PMID 34298795, 2021). "In metastatic tumors, pathway and TF analyses revealed strong hypoxia-inducible factor-1α–driven hypoxia activation, influencing glycolysis (SLC2A1, SLC2A3, PGK1, PDK1, PGM1, and ALDOA), angiogenesis (ANGPTL4 and ADM), and survival in low oxygen (BNIP3, BNIP3L, and NDRG1)." (PMID 40736012, 2025).
oral squamous cell carcinoma (5 papers, 2017 to 2023). "ACOX1 can be combined with MMP1, suppressor of cytokine signaling 3 (SOCS3) to diagnose oral squamous cell carcinoma (OSCC), and downregulation in bladder cancer might be due to PDK1 down-regulation, suggesting that it might serve as a potential biomarker and therapeutic target for bladder." (PMID 37724116, 2023).